U6 (U6 spliceosomal RNA )
Synonyms: LOC124906340
Gene: Small nuclear RNA gene on chromosome 3 (129,819,777 to 129,819,876, forward strand). Ensembl gene ENSG00000283509.
Gene Ontology:
Molecular function: U4 snRNA binding
Biological process: formation of quadruple SL/U4/U5/U6 snRNP; spliceosomal tri-snRNP complex assembly
Cellular component: U4/U6 x U5 tri-snRNP complex; U6 snRNP
Homologues: Orthologues: macaque U6 (91% identical), rat LOC120101173 (81% identical), dog U6 (71% identical). Paralogues in human: RNU6-1060P (84% identical), RNU6-116P (84% identical), RNU6-1145P (83% identical), RNU6-17P (83% identical), RNU6-18P (83% identical), RNU6-22P (83% identical), RNU6-33P (83% identical), RNU6-959P (83% identical), RNU6-1 (82% identical), RNU6-12P (82% identical), RNU6-13P (82% identical), RNU6-15P (82% identical), and 1285 more.